AR (androgen receptor)
Diseases named in the same sentence as AR in open-access papers (continued):
Sharing a sentence is not in itself a finding about the gene and the disease.
cancer (continued). "While chemotherapy and radiation primarily target highly proliferating cancer cells, ADT and ARSI aim to restrict PCa cells, whose proliferation is dependent on signaling by the androgen receptor (AR), an androgen-responsive transcription factor." (PMID 41327318, 2025). "For instance, depletion of AR in CAFs restored levels of IFN‐γ and MCSF, consequently inhibiting cancer cell proliferation in vitro." (PMID 40007149, 2025). "Based on the ALAN quantitative outputs, RSPO2 behaved similarly to EMT-related genes and FGFR1/2, but exhibited opposing behavior with AR regulatory genes and MYC, a pan-cancer oncogene." (PMID 40711886, 2025). "AR signaling in CAFs also suppresses pro-tumorigenic cytokines such as CCL2 and CXCL8, and AR inhibition increases their secretion, promoting cancer cell migration." (PMID 41584838, 2025). "Androgens can directly stimulate AR-positive cancer cells, while insulin and IGF promote mitotic activity in cancer cells." (PMID 40534880, 2025). "These techniques enable the evaluation of the interaction of phytochemicals with cancer-related molecular targets such as HIF-1α and the human androgen receptor." (PMID 40362546, 2025). "Furthermore, the AR blockade could disrupt reciprocal signaling between cancer cells and CAFs." (PMID 41584838, 2025). "For cancer-specific survival (CSS) and recurrence-free survival (RFS), only AR positivity demonstrated a significant prognostic impact, as shown in the Kaplan–Meier curves." (PMID 41463239, 2025). "In our study, the anti-cancer effect of NSC632839 in PCa was studied for the first time in the literature and also the expression level of SENP2 and its correlation with the androgen receptor (AR) in PCa tissue samples were evaluated using public databases." (PMID 40434722, 2025). "However, the application of AR antagonists may promote the expression of AR in cancer cells." (PMID 39927164, 2025). "This overlap between AR/AR-SV-suppressed oncogenic pathways in AR-SV(±) HCC and niclosamide’s anti-AR and anti-cancer activity well positions niclosamide as a potential HCC therapeutic that can address this complex signaling." (PMID 40805231, 2025). "We will explore the molecular mechanisms by which OCT4 regulates cancer stemness, EMT, and AR independence, as well as its interactions with key oncogenic pathways." (PMID 40722714, 2025). "These approaches uncover functional niches, including androgen receptor–driven TNBC (LAR subtype) and immune-excluded claudin-low cancers, thereby expanding the repertoire of actionable biomarkers and revealing novel therapeutic vulnerabilities." (PMID 41373752, 2025). "Although BPTF has previously been reported to promote the progression of multiple cancer types by regulating c-Myc activity, our study shows that BPTF primarily upregulates the AR transcriptional program in PCa." (PMID 41381516, 2025). "As discussed in the context of cancer, Cdk5 phosphorylates STAT3 and the androgen receptor (AR), enhancing their pro-proliferative transcriptional programs." (PMID 41369365, 2025). "Two structurally characterized receptors—the human androgen receptor (HAR, PDB ID: 1E3G) and hypoxia-inducible factor 1-alpha (HIF-1α, PDB ID: 3KCX), known for their involvement in cancer-related pathways, were used for molecular docking investigations." (PMID 40362546, 2025). "The finding that NRF2-dependent cancer cells are refractory to CBP/p300 inhibition distinguishes NRF2 from other transcriptional oncogene addictions (i.e., AR, BRD4-NUT)." (PMID 40369363, 2025). "The cancer genome profiling revealed deletion of BRCA 2 and PTEN, AR amplification, and the presence of the TMPRSS2-ERG fusion gene." (PMID 38428891, 2024).
cancer (continued). "Guided by the HTAN-SCLC cancer epithelium dataset, we further found that the RNA expression of ASCL1, PHOX2A and AR was regulated by ZNF536." (PMID 38720348, 2024). "First, by blocking phosphorylation of Ser2-RNAPII, CDKI-73 inhibits transcription and reduces levels of key cancer-promoting factors such as MYC, pro-survival members of the BCL-2 family, and AR." (PMID 39117800, 2024). "Inactivation of NSD2 also engendered increased dependency on its paralog NSD1, which independently maintained AR and MYC hyper-transcriptional programs in cancer cells." (PMID 38464251, 2024). "Such a mechanism underscores the complex interplay between hormonal signaling and epigenetic modifiers in cancer progression, where ING1 and ING2 emerge as critical mediators of AR’s transcriptional repressive functions on key oncogenic drivers." (PMID 38813086, 2024). "Although initial responses are generally positive, cancers often relapse, progressing to the castration-resistant stage of PCa (CRPC) with partially restored AR signaling." (PMID 38687617, 2024). "To investigate if the downregulation of ER-α and AR is an indirect consequence of the ERIs inducing the lysosomal degradation of HER3, we explored cancer genomics databases to determine if there is a correlation between HER3 and hormone receptor expression." (PMID 38228924, 2024). "For example, the GR, AR, Progesterone receptor (PGR), and ER boast 51, 25, 20, and 19 approved drugs (mainly anti-cancer), respectively." (PMID 39065726, 2024). "In PCa cells, the suppression of SIRT3 by the AR and its coregulator SRC-2 enhances ACO2 activity, promoting citrate synthesis and favoring aggressive cancer phenotypes." (PMID 39796040, 2024). "AR is expressed in multiple tissues, and it is positively correlated with six integrin genes in PRAD and also with other integrin genes in other cancer types (e.g., HNSC and CESC), indicating a weak cancer type specificity." (PMID 39436262, 2024). "They propose that apocrine phenotype and AR expression define SDC and that salivary malignancies which do not fit these criteria can almost always be reclassified as alternative cancer subtypes." (PMID 38539538, 2024). "Beyond its interaction with AR signaling, AHR has also been shown to engage with other cancer-relevant signaling pathways, including the Wnt/β-catenin, NF-κB, and MAPK pathways." (PMID 39600743, 2024). "The binding of androgen hormones to their receptors initiates androgen receptor (AR) signaling cascades, and activating this signaling plays a critical role in promoting cell growth, BPH, and cancer." (PMID 39830338, 2024). "To investigate this, we analysed publicly available cancer genomics datasets to determine if the expression of HER2 and HER3 is correlated with that of ER-α and AR." (PMID 38228924, 2024). "The SCENIC results suggest that normal and cancer epithelia share canonical luminal transcription factors (TFs) such as HOXB13, GATA2, AR." (PMID 38483933, 2024). "When grouped by ZNF536 expression, we found that in the cancer epithelium, ZNF536 exhibited co-expression with PHOX2B and AR, while being excluded from IFI27, IFI6, and ZFP36." (PMID 38720348, 2024). "In the hormone-like community, CpGs were enriched in binding regions of ER and AR, as well as FOX and GATA family TFs, known to be important in hormone signaling in cancer." (PMID 39556603, 2024). "After phosphorylation, this protein plays an essential role in AR stabilization, and the increase and decrease in SHP2 activity will increase the probability of malignant tumors." (PMID 39771106, 2024). "This is because AR is also a direct substrate of MDM2, and nutlin itself is known to induce the ubiquitination of AR in cancer cells." (PMID 38339414, 2024). "Some studies have accounted for predicted and validated gene targets like GATA2, SKI, NTRK3, PAK2, AR, SP1, and CDK4 that describe their involvement in cancer progression." (PMID 38741808, 2024).
cancer (continued). "Its interactions with the AR and steroidogenic enzyme HSD17B4 enhance aggressive cancer phenotypes and cell survival." (PMID 39796040, 2024). "Previous studies have reported an interaction between AR and FOXA1 in cell proliferation related to human cancer." (PMID 38397387, 2024). "Of these, AR and HER2 are the most commonly expressed changes in this cancer type; thus, immunohistochemical staining is often completed for these variants." (PMID 39659799, 2024). "In intermediate-grade cancer, NKX3.1 (Androgen receptor gene) showed positive correlations (ranging from 0.527 to 0.857) with Contrast T2WI, Correlation T2WI, Sum Square Variance T2WI, and Inverse Difference T2WI." (PMID 38791417, 2024). "The CTCs have variable expression for the epithelial and cancer-specific markers, such as EpCAM, EGFR, E-cadherin, mammaglobin, HER2, ER, and AR." (PMID 39594700, 2024). "Biopsy specimen for cancer genome profiling revealed deletion of BRCA 2 and PTEN, AR amplification, and the presence of the TMPRSS2-ERG fusion gene." (PMID 38428891, 2024). "Recent cancer genomics studies have also supported transdifferentiation, as NEPC often exhibits genetic alterations reminiscent of AR-dependent CRPC." (PMID 37446279, 2023). "Clinically, the effectiveness of PCa drugs on cancer progression can be evaluated by measuring PSA levels or, more recently, by evaluating or genotyping the AR protein that is present." (PMID 37046780, 2023). "Both the TF activity and expression of androgen receptor (AR) and sterol regulatory element binding transcription factor 1 (SREBF1) showed significant upregulation in cancer cells from MBC, compared with FBC." (PMID 37696831, 2023). "Reports suggest that AR and YAP co-localise and interact in the nucleus to promote cancer progression and that this interaction is critical for AR function." (PMID 37385752, 2023). "Diarylisoxazole derivatives exhibited anti-cancer activity against MDA-MB-453 cells, a model of the luminal androgen receptor subtype of TNBC." (PMID 37744269, 2023). "It exerts its suppressive effect on cell growth by inhibiting the expression of integrin β1 and the activation of AR and FAK, thereby impeding cancer cell proliferation." (PMID 37681860, 2023). "The workflow involves the same exclusion criteria as the non-cancer TTC in addition to exclusion of chemicals that are expected to have potent chemical/receptor interactions with the estrogen and/or androgen receptor." (PMID 36149470, 2023). "ChIP-seq Enrichment Analysis (ChEA) for these up-regulated genes in the KO cells demonstrated over-representation of transcription factors of SUZ12, AR, Nrf2, SMAD4, as well as SOX2 and Nanog important for the stem cells and cancer stem cells." (PMID 37151890, 2023). "Hence, the design of future studies may incorporate the use of statins with one of the androgen receptor pathway inhibitors, requiring the recruitment of large patient numbers with extended duration of statin treatment to fully test the long‐term anti‐cancer effects of statins." (PMID 35844167, 2023). "The high heterogeneity across TNBC subtypes, which can be classified to be at least four subtypes, including two basal-like (BL1, BL2), a mesenchymal (M), and a luminal androgen receptor (LAR) subtype, limits the response to cancer therapies." (PMID 36672350, 2023). "Additionally, three other NADBPs, which mutations are implicated in cancer, were found in the catalogue of FDA approved targets, namely, 5-aminoimidazole-4-carboxamide ribonucleotide formyltransferase/IMP cyclohydrolase (ATIC), androgen receptor (AR) and isocitrate dehydrogenase 2 (IDH2)." (PMID 36880517, 2023). "On the other hand, in hormone-independent VCap cells, EGFR, AR, and Matrix Metalloproteinase-9 (MMP-9) are reported to cooperate to promote cancer progression." (PMID 37463954, 2023).
cancer (continued). "We have previously reported that 5-oxo-ETE triggers actin cytoskeleton rearrangements in prostate DU145 cancer cells, which highly express OXER1 but lack AR, leading to an increase in formation of stress fibers and an increased migratory capacity." (PMID 38202807, 2023). "Meanwhile, the transcriptionally active AR induced KIF15 expression, which generated a positive feedback system that promotes drug resistance and cancer progression." (PMID 36807568, 2023). "It appears to regulate a switch to an androgen-independent form of cancer, castration-resistant prostate cancer (CRPC), which frequently still requires androgen receptor (AR) signalling." (PMID 37363926, 2023). "A study on the exosome regulatory network and CaP chemoresistance linkage revealed that exosome miRNAs regulate AR, PTEN, and TCF4 genes in chemoresistant cancer cells." (PMID 37895357, 2023). "For example, PROTACs targeting AR, BR, BTK, Tau, IRAK4, and other proteins have shown unprecedented clinical efficacy in cancers, neurodegenerative diseases, inflammations, and other fields." (PMID 36142231, 2022). "CYP17A1 can maintain intratumor androgen levels that are sufficient enough to reactivate AR signaling in CRPC and promote the resurgent growth of the cancer lesion." (PMID 36430730, 2022). "Therefore, we suggest that dual activation of ERβ and PGR by their ligands could initiate a cascade of cellular anti-cancer events involving inhibition of cancer progression induced via AR and ERα pathways alongside promoting anti-proliferative and pro-apoptotic activities." (PMID 36263327, 2022). "In CPTAC-ccRCC, the protein expression of genes AR, GNB3, HHLA2, LIMCH1, and SAA1 had statistical significance in some comparisons of normal samples and cancer stage (Figure A9a–e)." (PMID 35565241, 2022). "Testosterone and selective androgen receptor modulators (SARMS) have been suggested and studied as interventions against cancer induced wasting." (PMID 35694399, 2022). "Six cancer-specific signaling pathways—The irinotecan pathway, metabolism, androgen receptor signaling, interferon signaling, MAPK/NF-kB signaling, and the tamoxifen pathway—were identified, and 86 genes were involved in these cancer-specific pathways." (PMID 36289913, 2022). "Co-inhibition of androgen receptor (AR) and PARP proteins results in cancer cells’ inability to repair DNA." (PMID 35159068, 2022). "Based on data from The Cancer Genome Atlas (TCGA), the expression of ZMIZ2 in different subtypes and its correlation with androgen receptor (AR) were analyzed, and a regulatory mechanism network was constructed." (PMID 35101047, 2022). "Pathway analysis revealed that selinexor-treated CF365 tumors had upregulation of the β-catenin degradation pathway, modulated WNT signaling and androgen receptor signaling, which is in line with the known effects of XPO1 inhibition in cancer cells." (PMID 36059685, 2022). "Regarding AR-related signaling, a growing amount of literature investigates the complex crosstalk with VEGF-mediated pathways in cancer." (PMID 35222436, 2022). "One study looking at the role of AR and EMT in breast, prostate, and other cancer cells found that AR directly downregulated E-cadherin expression through an ARE leading to EMT and metastases." (PMID 36430245, 2022). "Thus, AR-directed therapies in CAFs might help the therapeutic approach of different cancer types." (PMID 35222290, 2022). "The histone demethylase PHD-finger protein 8 (PHF8) is upregulated in PCa, acts as a transcriptional coactivator of AR via H4K20 demethylation and promotes cancer cell proliferation, migration, invasion, and neuroendocrine differentiation." (PMID 35205419, 2022).
cancer (continued). "Immunostaining for AR, CK8, high-molecular weight keratin (HMWCK), TOPK, c-MYC, and N-MYC demonstrated differential levels of CK8 and N-MYC in AP3 cancer and normal cells with HMWCK as a basal marker." (PMID 36970725, 2022). "Interestingly, cancer samples with an AR mutation (AR+, n = 101) showed significantly lower levels of miRNAs 148a-3p, 148b-3p, 195-5p, 210-3p, 23a-3p, 25-3p when compared to samples without an AR mutation (AR–, n = 96)." (PMID 35053623, 2022). "The steroid-activated androgen receptor (AR) can also decrease the c-MYC signaling pathway, which accounts for driving reinforced glutaminolysis in cancer cells through regulating glutamine transporters and GLS1 directly or indirectly (via miRNA)." (PMID 36077501, 2022). "In fact, in addition to PTGS2, the mRNA expression of AR was also significantly upregulated in PDAC samples (and other five cancers) compared with normal samples (FC > 1.6, p < 0.01)." (PMID 35701649, 2022). "Therefore, multipoint targeting of the AR signaling pathway may accomplish the same or even greater antitumor effect while reducing side-effects, which may slow down the induction of resistance and cancer progression." (PMID 35864113, 2022). "Next, we assessed aberrant AR, IGF1, and Wnt/β-catenin signaling pathways in both human primary PCa samples from the TCGA Pan-Cancer Atlas and advanced PCa samples in cBioPortal33,34." (PMID 35902588, 2022). "In NEPC, even the classical marker PSA is less accurate for diagnosis, staging, and monitoring cancer burden, as NEPC cells are AR independent." (PMID 35447888, 2022). "Comparative analysis in more advanced and metastatic cancers showed that APC alterations were enriched in these types of cancer, while alterations in ATM and amplifications in AR were specifically enriched in CRPC." (PMID 35205419, 2022). "It is well established that cancer-cell proliferation is impaired upon FOXA1 depletion since ER and AR transcription is FOXA1-dependent both in breast and prostate cancer cells." (PMID 36230619, 2022). "Expression of AR variants, namely AR-V7, is not cancer specific as it is detected in several human tissues including liver, spleen, placenta, brain, small intestine, and white blood cells indicating that AR variants likely have a physiological function which is currently unknown." (PMID 35948987, 2022). "Among the cancer-related signaling pathways, GRGs had high levels of activation in epithelial-mesenchymal transition (EMT), hormone androgen receptor (AR) and cell cycle signaling pathway." (PMID 36339430, 2022). "Since androgen receptor (AR) is essential for the function, survival, and differentiation of prostatic tissue, ADT reduces androgens necessary to block cancer progression." (PMID 35800367, 2022). "In contrast, levels of AR and PARD3B mRNAs in most of TCGA cancer types were downregulated compared to their respective normal tissues." (PMID 36013056, 2022). "However, the molecular regulation of AR in each type of cancer remains unclear." (PMID 35886904, 2022). "In contrast, levels of AR and PARD3B mRNA in most TCGA pan-cancer types were downregulated compared to their respective normal tissues." (PMID 36013056, 2022). "ARV-110 uses PROTAC technology to degrade AR protein and has been developed as a potential treatment for metastatic CRPC, which is the second most prevalent cancer in men." (PMID 35370971, 2022). "In conclusion, apigetrin induces anti-cancer effects by regulating AKT, a key transmitter of HIF-1α and AR signaling in PCa cells." (PMID 35740392, 2022).